PFKFB3 (6-phosphofructo-2-kinase/fructose-2,6-biphosphatase 3)
Diseases named in the same sentence as PFKFB3 in open-access papers (continued):
Sharing a sentence is not in itself a finding about the gene and the disease.
gastric cancer (continued). "6-phosphofructo-2-kinase/fructose-2, 6-biphosphatase 3 (PFKFB3) is one of the critical enzyme of the glycolytic pathway and an increased mRNA expression of PFKFB3 is well documented in aggressive neoplasm of ovary, colon and breast and in gastric cancer tissue." (PMID 39342193, 2024). "PFKFB3 inhibitor 3-(3-pyridinyl)-1-(4-pyridinyl)-2-propen-1-one (3PO) and its derivation 1-(4-pyridinyl)-3-(2-quinolinyl)-2-propen-1-one (PFK15) have been confirmed to inhibit glucose metabolism and exert potent antitumor activity in multiple cancers, especially gastric cancer." (PMID 35094634, 2022). "In gastric cancer, PFKFB3 is preferentially expressed in tumors with lymph node metastasis." (PMID 35155224, 2022).
hepatocellular carcinoma (24 papers, 2018 to 2025). A malignant tumor that arises from hepatocytes. "In this study, we found that PFKFB3 expression is associated with hepatocellular carcinoma (HCC) growth and located mainly in the nucleus of tumor cells." (PMID 29559632, 2018). "PFKFB3 knockdown inhibited hepatocellular carcinoma cell proliferation by impairing DNA repair functions." (PMID 37253634, 2023). "The PFKFB3/AKT/ERCC1 (Excision repair cross-complementation group 1) pathway has been reported to promote the progression of hepatocellular carcinoma by enhancing DNA repair in the process of glycolysis." (PMID 36973739, 2023). "Mechanistically, blockade of PFKFB3 inhibits hepatocellular carcinoma growth by impairing DNA repair via AKT." (PMID 36213162, 2022). "PFKFB3 was found to be central element of the mechanism of metabolic switch that regulates the pro-tumor programming of monocytes in human hepatocellular carcinoma." (PMID 36733385, 2022). "A recent study revealed that up-regulation of PFKFB3 promoted immune evasion and tumorigenesis by inducing PD-L1 expression through NF-κB activation in hepatocellular carcinoma." (PMID 35155224, 2022). "Silencing of PFKFB3 decreases glucose consumption and inhibits DNA repair; thus, suppressing tumor growth in hepatocellular carcinoma." (PMID 35155224, 2022). "In their study, PFKFB3 knockdown inhibited hepatocellular carcinoma cell proliferation by impairing DNA repair functions, which resulted in G2/M phase cell cycle arrest." (PMID 33671514, 2021). "PFKFB3 expression is also linked to hepatocellular carcinoma (HCC) growth." (PMID 30234009, 2018). "The effects of PFKFB3 blockade extend to other cancers such as hepatocellular carcinoma (HCC)." (PMID 39567756, 2025). "Likewise, Metformin can attenuate hepatoma cell proliferation by decreasing glycolytic flux via the HIF-1α/PFKFB3/PFK1 pathway and overcome MR-induced resistance of skin carcinoma to photodynamic therapy." (PMID 39588377, 2024). "However, the exact role of regulation of HIF-1α/PFKFB3 in the pro-invasion effect induced by sorafenib in hepatocellular carcinoma needs further investigation." (PMID 37476196, 2023). "In addition, aspirin has been reported to overcome sorafenib resistance in hepatocellular carcinoma by blocking PFKFB3, and inhibition of PFKFB3 also reduces DNA repair to control the growth of hepatocellular carcinoma." (PMID 37397026, 2023). "A recent study indicated that PFKFB3 overexpression could increase immune evasion and tumorigenesis in hepatocellular carcinoma by NF-κB activation and enhance PDL1 expression and could regulate the NF-κB pathways in ovarian cancer." (PMID 36016583, 2022). "Interestingly, PFKFB3 expression has been found to occur mostly within the nucleus in certain cancers, such as hepatocellular carcinoma (HCC)." (PMID 34831136, 2021). "In monocyte-derived peritumoral macrophages in hepatocellular carcinoma (HCC), PFKFB3 was found to modulate the metabolic switch and the increased NF-κB-dependent PD-L1 expression." (PMID 41516095, 2025). "PFKFB3 is a rate-limiting enzyme that has a strong kinase activity promoting the formation of F2,6BP and is usually upregulated in a wide variety of tumors, including hepatocellular carcinoma, where F2,6BP acts as an allosteric modulator promoting the activation of the glycolytic flux." (PMID 36914921, 2023). "Overexpression of PFKFB3 followed by glycolysis is responsible for Hepatocellular carcinoma (HCC) resistance to sorafenib." (PMID 33671514, 2021). "Studies have shown that PFKFB3 acts as a glycolytic activator to promote the growth of hepatocellular carcinoma and induce tumor angiogenesis, whereas inhibition of PFKFB3 prevents glycolycolytic mediated HCC proliferation." (PMID 37397026, 2023).
hepatocellular carcinoma (continued). "PFKFB3-NF-κB signaling induced the production of CXCL2 and CXCL8 in tumor-infiltrating monocytes, increased levels of CXCL2 and CXCL8 in monocytes and promote infiltration of oncostatin M-producing neutrophils in human hepatocellular carcinoma tissues." (PMID 37253634, 2023). "A recent study showed that high expression of PFKFB3 induces CD274 molecule (CD274) expression via activating the NF-κB signal pathway in monocytes, therefore inhibiting CD8+ T cell activity and poor prognosis in hepatocellular carcinoma patients." (PMID 37253634, 2023). "Importantly, our analysis confirmed the previously published negative impact of PFKFB4 on the prognosis of glioma patients and negative impact of PFKFB3 on the prognosis of hepatocellular cancer." (PMID 31754349, 2019). "It cannot be ruled out that PFKFB3 protein is induced at later stages of hypoxia, since it was reported that metformin suppressed PFKFB3 expression by preventing HIF-1α accumulation in hepatoma cells, thereby inhibiting glycolysis and proliferation." (PMID 35072776, 2022).
colorectal cancer (23 papers, 2016 to 2026). A primary or metastatic malignant neoplasm that affects the colon or rectum. "In the colon, research predominantly targets PFKFB3’s role in colitis-associated colorectal cancer, leaving its function in UC relatively unexplored." (PMID 41378888, 2026). "The high PFKFB3 expression level was significantly associated with recurrence in patients with colorectal cancer (p=0,046)." (PMID 36733385, 2022). "In studies of colitis-associated colorectal cancer (CRC), PFK158 was shown to effectively inhibit PFKFB3-driven CRC cell proliferation, migration, and invasion." (PMID 41378888, 2026). "Treatment with IL-6 promotes expression of the glycolytic genes SLC2A1, HK2, PKM2, PFKFB3, and LDHA in human colorectal cancer cells, and similarly induces Hk2, Pkm2, and Pfkfb3 expression in murine macrophages." (PMID 39433211, 2025). "In this study, we have explored the effects of PFKFB3 inhibition by 3PO in vitro and in vivo using endothelial cells, colorectal cancer cells, PDOs, and PDXs." (PMID 39007350, 2024). "For cancer type, combining these results indicated that PFKFB3 has a remarkably high expression in TME in colorectal cancer (CRC) and HNSC." (PMID 37253634, 2023). "The inhibition of 6-Phosphofructo-2-Kinase/Fructose-2,6-Biphosphatase 3 (PFKFB3) enhanced the sensitivity of NSCLCs to erlotinib by decreasing autophagy, and inhibiting glycolysis was shown to overcome taxol-resistance in colorectal cancer cells." (PMID 36076996, 2022). "KAN, an emerging selective inhibitor of key rate-limiting metabolic kinase PFKFB3, has been used to treat colorectal cancer and elevate the efficacy of interstrand crosslink- (ICL-) inducing cancer therapies due to the function during DNA damage." (PMID 36187335, 2022). "circ_0014130 acted as a molecular sponge for miR-197-3p and participated in the drug sensitivity and development of colorectal cancer by regulating the miR-197-3p/PFKFB3 axis." (PMID 36065412, 2022). "In sum, these data show that PFKFB3 expression is found enhanced in colorectal cancer and its expression inversely correlates with the survival of colon and in trend of rectal cancer patients." (PMID 33671096, 2021). "Resistance to oxaliplatin (used to treat colorectal cancer) often involves the upregulation of autophagy that correlates with increased levels of PFKFB3." (PMID 33671514, 2021). "Inhibition of PFKFB3 suppresses defensive autophagy induced by oxaliplatin and recovers cytotoxicity of oxaliplatin in colorectal cancer." (PMID 34540667, 2021). "Collectively, the presented data demonstrated that PFKFB3 inhibition attenuated Oxa-induced autophagy and enhanced its cytotoxicity in colorectal cancer cells." (PMID 31671668, 2019). "In contrast, inactivation of Pfkfb3 activity has also been shown to elicit the compensatory activation of autophagy, thereby enhancing the survival of colorectal cancer cells." (PMID 31413316, 2019). "The cytokine IL-6 increases glycolysis by inducing PFKFB3 expression through STAT3 activation, suggesting a functional role of PFKFB3 in chronic inflammation and in the development of colorectal cancer." (PMID 30234009, 2018). "We have evaluated in vitro and in vivo the effects of the PFKFB3 inhibitor 2E-3-(3-pyridinyl)-1-(4-pyridinyl)-2-propen-1-one (3PO) on cell survival, clonogenicity, migration, invasion, and metabolism using colorectal cancer cells, patient-derived tumor organoid (PDO), and xenograft (PDX)." (PMID 39007350, 2024). "On the final step, we assessed the prognostic significance of PFKFB3 in colorectal cancer." (PMID 36733385, 2022). "PFKFB3 increased IL-1β and TNF-α in intestinal epithelial cells to promote colitis-related colorectal cancer tumorigenesis." (PMID 38098990, 2023).
colorectal cancer (continued). "The aim of this study was to evaluate PFKFB3 expression and its correlation with outcome in rectal and colon tumors and to assess the effects of the newly developed PFKFB3 inhibitor KAN0438757 on colorectal cancer cells and intestinal patient-derived organoids." (PMID 33671096, 2021). "In addition to PKM2, PFKFB3, and FASN, there are no available reports about the role of HMGCS2 and angiogenesis in various cancers, including colorectal cancer." (PMID 31355161, 2019).
colon carcinoma (18 papers, 2014 to 2025). "We found that the stromal infiltration of PFKFB3+ cells is significantly elevated in colorectal tumors, particularly in colon cancer, and is associated with increased infiltration of pro-tumoral macrophages." (PMID 41516095, 2025). "In colon cancer, PFKFB3 overexpression correlated with a higher risk of tumor relapse and poor survival rates." (PMID 41516095, 2025). "Using NanoString GeoMx, we found that in colon tumor tissue, PFKFB3 expression was linked to TAM accumulation and M2 polarization." (PMID 39516356, 2024). "Next, by considering the combined biomarkers, we defined two molecular metabolism phenotypes of colon cancer: a glycolysis‐proficient phenotype (glycolysis+) with either GLUT1 or PFKFB3 overexpression and a ketolysis‐deficient (ketolysis−) phenotype by null expression of either OXCT1 or ACAT1." (PMID 36031388, 2022). "We followed the fate of PFKFB3+ monocytes in colon cancer, and using spatial transcriptomics demonstrated their massive infiltration and differentiation into PFKFB3+CD68+." (PMID 41516095, 2025). "We recently identified a new TAM-expressed marker for unfavorable prognosis in colon cancer—a regulator of glycolysis, PFKFB3." (PMID 39516356, 2024). "PFKFB3 expression correlated to M2-polarized macrophages and indicated poor prognosis in colon cancer patients." (PMID 39315092, 2024). "have convincingly illustrated that monocytes, isolated from the peripheral blood of patients with colon cancer, demonstrate pronounced upregulation of 6-phosphofructo-2-kinase/fructose-2,6-biphosphatase 3 (PFKFB3), a key enzyme in the glycolytic cascade." (PMID 38193086, 2023). "GeoMX DSP-NGS analysis of colon cancer patients identified the correlation of PFKFB3 expression with monocytes infiltration and M2-type polarization markers, including CD163, CD206, CD204 and MARCO." (PMID 36733385, 2022). "We focused on glycolytic activator 6-phosphofructose-2-kinase and fructose-2,6-bisphosphatase (PFKFB3), which demonstrated most significant differences in colon cancer." (PMID 36733385, 2022). "Our data for the first time demonstrate that colon cancer affects circulating monocytes transcriptome and induces elevation of PFKFB3 expression." (PMID 36733385, 2022). "RNAseq analysis validated by RT-PCR allowed to identify specific upregulation of glycolytic activator PFKFB3 monocytes of colon cancer patients compared to healthy individuals and to patients with rectal cancer." (PMID 36733385, 2022). "The positive correlation between PPFIA4 and ENO2/PFKFB3 levels also corroborated that PPFIA4 was a potential regulator of glycolysis in colon cancer." (PMID 34094943, 2021). "The addition of PFK-15 (PFKFB3 inhibitor) to colon cancer cells results in attenuation of autophagy and induction of cytotoxicity." (PMID 33671514, 2021). "In malignant human colon tumors, PFKFB3 overexpression and phosphorylation of its S461 residue (P-PFKFB3 S461) has been observed." (PMID 30234009, 2018). "Within the CRC cohort, the CC subgroup maintained significantly higher PFKFB3 expression than RC (1.4-fold increase; 34.50 ± 27.37 vs. 24.72 ± 21.53, p < 0.045), corroborating prior monocyte data and underscoring a specific role for PFKFB3 in colon cancer pathogenesis." (PMID 41516095, 2025). "PFKFB3+CD68+ correlated with unfavorable prognosis specifically in colon cancer." (PMID 41516095, 2025). "In our recent study PFKFB3 was indicated as a prognostic biomarker for colon cancer." (PMID 39315092, 2024). "Moreover, PFKFB3 expression was upregulated in colon cancer patients with larger tumor size (T3-4) compared to patients with smaller tumor size (T1-2) (FC=1,4, p<0,0001)." (PMID 36733385, 2022). "PFKFB3 was indicative for tumor relapse specifically in colon cancer." (PMID 36733385, 2022). "We questioned whether PFKFB3-positive monocytes infiltrate colon cancer tissue." (PMID 36733385, 2022).
colon carcinoma (continued). "PFKFB3 mRNA expression is negatively correlated with relapse and poor OS and PFS in colon cancer patients." (PMID 39516356, 2024). "A new finding in the present study is that Oxa induces autophagy with a concomitant promotion of PFKFB3 expression at both mRNA and protein levels in SW480 colon cancer cells." (PMID 31671668, 2019). "Co-expression analysis revealed that ACSL1 was coexpressed with MYBPH, PTPRE, PFKFB3, SOCS3 in colon cancer and with LRRFIP1, TSC22D1 in lung cancer." (PMID 27171439, 2016). "Interestingly, post-surgery levels of PFKFB3, IL1b, HSPA1B and DDIT4 in colon cancer were increased compared to control." (PMID 36733385, 2022). "PPFIA4 silencing could be a strategy for reprogramming glycolysis of colon cancer, and its efficacy is dependent on ENO2/PFKFB3." (PMID 34094943, 2021). "Thus, PFKFB3 was found as a prognostic factor for tumor relapse and unfavorable outcome in patients with colon cancer, but not with rectal cancer." (PMID 36733385, 2022).
glioblastoma (16 papers, 2013 to 2025). The most malignant astrocytic tumor (WHO grade IV). "Our findings indicate different roles for splice variants PFKFB3-4 and PFKFB3-5 in healthy as well as malignant cells and implicate an important diagnostic role of these specific PFKFB3 splice variants in glioblastomas." (PMID 34234350, 2021). "The PFKFB3 isozymes have been identified as one of the major metabolic players in glioblastoma however, thus far the functional relevance of PFKFB3 splice variants is only partially understood." (PMID 34234350, 2021). "Up to now, the role of PFKFB3 splice variants in the progression and prognosis of glioblastomas is only partially understood." (PMID 34234350, 2021). "In conclusion, we provide experimental and clinical evidence suggesting the significance of a specific PFKFB3 splice variant (PFKFB3-4) as a growth promoting factor in glioblastoma." (PMID 34234350, 2021). "In addition, here we first report on the role of the novel splice variant PFKFB3-5 in glioblastoma, which contrasts the prevailing growth-promoting function of PFKFB3." (PMID 34234350, 2021). "In conclusion, increased proliferation rates in highly malignant glioblastomas as well as in glioblastoma cell lines might be causally related to the high PFKFB3-4 to -5 expression ratio in which PFKFB3-4 is showing strong growth promoting effects." (PMID 34234350, 2021). "Our findings indicate that the expression level of distinct PFKFB3 splice variants impinges on tumorigenic properties of glioblastomas and that splice pattern may be of important diagnostic value for glioblastoma." (PMID 34234350, 2021). "A reduction of total PFKFB3 level by allelic deletion might lead to decreased Fru-2,6-P2 levels, which might result in decreased rate of glycolysis: a hallmark of glioblastomas." (PMID 24280138, 2013). "Although tRiMetF31 was also downregulated in three glioblastoma cell lines (A-172, M059J, and M059K), PFKFB3 was undetectable in all three glioblastoma lines." (PMID 35961977, 2022). "Of particular relevance to glioblastoma is the finding that PFKFB3:PFKFB4 mRNA ratios are of prognostic value to high grade glioma, with increasing PFKFB4 levels correlating unfavorably with patient survival." (PMID 36115843, 2022). "PFKFB3 overexpression in glioblastoma by TGF-β1 is primarily through transcriptional upregulation mediated by the Smad pathway." (PMID 34831136, 2021). "In IDH-wildtype glioblastomas we also found a significant shift towards PFKFB3-4 expression compared to PFKFB3-5, whereas the PFKFB3-4 to -5 ratio in normal brain tissue was also near 1:1." (PMID 34234350, 2021). "Consistent with the idea that PFKFB3-4 possesses tumor inhibiting features, the loss-of-heterozygosity (LOH) of the PFKFB3 gene locus, which negatively affects the prognosis of glioblastoma patients was identified." (PMID 34234350, 2021). "In glioblastomas only three PFKFB3 transcripts -1, -4 and -11 (former UBI2K4, 5 and 6) were detected, with decreased mRNA levels documented for PFKFB3-4, compared to low-grade astrocytomas and normal brain tissue." (PMID 34234350, 2021). "LOH on 10p14-p15 results in allelic deletion of the PFKFB3 gene with a resultant decrease in transcript levels and protein expression in 55% of glioblastomas." (PMID 34831136, 2021). "Glioblastomas are known to upregulate PFKFB3 expression following anti-VEGF treatment as a form of AAT resistance." (PMID 34831136, 2021). "A low PFKFB3:PFKFB4 mRNA ratio (7.7:1) has been found to be a poor prognostic factor in patients with IDH-wildtype primary glioblastoma." (PMID 34831136, 2021). "We investigated the impact of increased and decreased levels of PFKFB3-4 (former UBI2K4) and PFKFB3-5 (former variant 5) on the viability and proliferation rate of glioblastoma U87 and HEK-293 cells." (PMID 34234350, 2021).